MFAP2 (microfibril associated protein 2)
Diseases named in the same sentence as MFAP2 in open-access papers (continued):
Sharing a sentence is not in itself a finding about the gene and the disease.
endometriosis (1 paper, 2019). The growth of functional endometrial tissue in anatomic sites outside the uterine body. "Other study found MFAP2 as differentially expressed in severe vs. mild endometriosis." (PMID 31552087, 2019).
oesophageal cancer (1 paper, 2023). "Through the integration of data information, it was found that the variable shear factor QKI was closely related to the epithelial mesenchymal transformation (EMT) of oesophageal cancer, and QKI might promote the EMT process by activating the expression of IL-11, MFAP2, MMP10 and MMP1." (PMID 37428781, 2023).
triple-negative breast carcinoma (1 paper, 2024). An invasive breast carcinoma which is negative for expression of estrogen receptor (ER), progesterone receptor (PR), and human epidermal growth factor receptor 2 (HER2). "While the involvement of MFAP2 in metabolic disorders has been documented, its expression and prognostic significance in triple-negative breast cancer (TNBC) remain unexplored." (PMID 38822944, 2024).
uterine carcinosarcoma (1 paper, 2022). A usually aggressive malignant neoplasm arising from the uterine corpus and less often the cervix. "In addition, amplification was the only type of MFAP2 mutation in the uterine carcinosarcoma samples, with a mutation frequency of over 3%." (PMID 35211173, 2022).
ZIKV infection (1 paper, 2021). "Given the separation of Prc1+ and MFAP2+ populations, we next tested whether these groups were differentially vulnerable to ZIKV infection by multiplexing RNAscope probes against Prc1, MFAP2, and ZIKV." (PMID 34272257, 2021).
cancer (29 papers, 2011 to 2026). A tumor composed of atypical neoplastic, often pleomorphic cells that invade other tissues. "Recent research has indicated that MFAP2, recognized as a reliable prognostic marker in various cancers, is linked to tumor initiation and progression." (PMID 38894711, 2024). "Third, MFAP2 (microfibril-associated protein 2) plays a vital role in the regulation of the integrin signal pathway in cancer cell-ECM (extracellular matrix) interaction." (PMID 36936373, 2023). "Identifying and utilizing MFAP2 involvement in cancer will help develop new diagnostic, therapeutic, and prognostic methods for patients with malignant tumors." (PMID 36530974, 2022). "Aims: microfibrillar-associated protein 2 (MFAP2), a component of the extracellular matrix, plays key roles in regulating growth factor signal transduction and various malignant tumors." (PMID 36204318, 2022). "In addition, MFAP2 expression was also associated with tumor mutation burden, microsatellite instability, and neoantigens in different cancer types." (PMID 35211173, 2022). "MFAP2 was recently reported to be associated with various malignant tumors." (PMID 36204318, 2022). "Our results suggested that aberrant expression of MFAP2 was associated with its altered promoter methylation, affected immune infiltration in the tumor microenvironment, and also acted as a prognostic risk factor for a variety of cancers." (PMID 35211173, 2022). "Cancer-associated fibroblast is also an important regulator in matrix remodeling and whether it can secrete MFAP2 and participate in the deposition of MFAP2 are also worth studying." (PMID 32054827, 2020). "The present study combined several databases and performed a pan-cancer analysis of the expression profile, methylation, and mutation for MFAP2 and its implications for prognosis and immune infiltration, suggesting that MFAP2 could contribute to malignant properties of many tumors." (PMID 35211173, 2022). "Mechanistically, we established that CAFs-derived MFAP2 interacts with integrin β8 (ITGB8) on cancer cell surfaces, activating the integrin-FAK-ERK1/2 signaling cascade to drive CRC progression." (PMID 41617683, 2026). "MFAP2 contributes to cancer progression and drug resistance by activating the FAK-AKT signaling pathway, Notch1 pathway, and Wnt/β-catenin signaling pathway." (PMID 40228435, 2025). "It has been reported that MFAP2 promotes the progression of malignant tumors through multiple processes." (PMID 40657371, 2025). "Recently, a single-cell RNA sequencing study found that microfibril-associated protein-2 (MFAP2), an ECM glycoprotein that mainly functions to control ECM deposition, is associated with chemoresistance in cancer." (PMID 38562556, 2024). "MFAP2 is a biomarker of ECM that enhances B16 melanoma cancer cell motility and invasion in vitro and in vivo research studies." (PMID 39003454, 2024). "So, we used cBioPortal database to analyze the genomic alterations of MFAP2 in the TCGA pan-cancer datasets, consisting of 10,967 samples from 32 studies." (PMID 35211173, 2022). "The correlation of MFAP2 expression with immune infiltration in cancers was also analyzed in TISIDB database." (PMID 35211173, 2022). "Studies on the MFAP2 mechanism of action are expected to provide new strategies and novel therapeutic markers for cancer treatment." (PMID 36530974, 2022). "Despite these approaches, the specific functions of MFAP2 in cancer remain uncertain, and this possibility must be addressed experimentally with specific pharmacological tools." (PMID 36530974, 2022). "Numerous studies have shown abnormal MFAP2 levels and its effects on prognosis in different cancers, highlighting its significance in tumor progression, particularly during epithelial-mesenchymal transformation (EMT), because of its association with TGF-β." (PMID 36530974, 2022). "MFAP2 has the ability to determine the phenotype of cancer cells through altering ECM in cancer microenvironment." (PMID 35333898, 2022).
cancer (continued). "In light of novel data on microfibril-related proteins, including the role and mechanism of MFAP2 in tumors, we focused on the role and mechanism of MFAP2 in cancer to provide an updated review." (PMID 36530974, 2022). "This article reviewed the possible mechanism of MFAP2 in tumorigenesis and progression and provided a reference for the clinical prognosis of patients with cancer and new therapeutic target discovery." (PMID 36530974, 2022). "The results of the examination of subgroups based mainly on the nodal metastasis, the nature of most cancer stages, and the grade of tumors suggested that the MFAP2 mRNA grades of STAD patients were substantially higher than the corresponding group." (PMID 35356627, 2022). "KEGG enrichment results confirmed that MFAP2 was involved in cytokine-cytokine receptor interaction, transcriptional misregulation in cancer, ECM-receptor interaction, focal adhesion, and the IL-17 signaling pathway." (PMID 36204318, 2022). "Here, we retrieved multiple databases, GTEx, CCLE, Oncomine, TCGA, UALCAN, GEPIA2, and TISIDB, to analyze MFAP2 expression in pan-cancer and its relationship with prognosis." (PMID 35211173, 2022). "In view of the immunosuppressive effects of Th2 cells and M2 macrophages in cancer, we investigated the relationship between their infiltration levels and MFAP2 expression." (PMID 36204318, 2022). "MFAP2 plays an important role in the extracellular deposition, and few studies have explored the role of MFAP2 in cancers." (PMID 31962291, 2020). "MFAP2 plays a vital role in the regulation of integrin signal pathway in cancer cell–ECM interaction." (PMID 32054827, 2020). "We also demonstrate that the novel oncogene MFAP2 endows cancer cells by activating integrin signaling." (PMID 32054827, 2020). "Predictably, MFAP2 dysregulation will greatly change the status of ECM in cancer microenvironment and further modulate the phenotypes of cancer cells." (PMID 32054827, 2020). "MFAP1, MFAP2 and MFAP3 were up-regulated in both EAC and ESCC, while MFAP4 and MFAP5 were down-regulated in cancer tissues, indicating that MFAP2 might play crucial role in ESCC." (PMID 40657371, 2025). "Furthermore, qRT-PCR results from our specimens verified an over-expression of ASCL2, CREB3L3, and MFAP2 in the cancer cells compared with the normal cells." (PMID 36936373, 2023). "In conclusion, the MFAP2 mechanism in various cancers requires further exploration." (PMID 36530974, 2022). "MFAP2 has been reported to play an oncogenic role in several types of human cancers." (PMID 35211173, 2022). "In the last decade, aberrant expression of MFAP2 was found in various malignant tumors." (PMID 35211173, 2022). "Moreover, the expression of MFAP2 was significantly correlated with the pathological stage, grade, and prognosis of many cancers, suggesting that MFAP2 played an oncogene role in many tumors." (PMID 35211173, 2022). "Thus, changes in the expression of many of our proposed markers (including COL6A3, MFAP2 and MFAP5) can indicate the transition of normal fibroblasts to a cancer-associated state (e.g., in in vitro experiments)." (PMID 36263012, 2022). "MFAP2 expression and its effects on prognosis in different types of cancers." (PMID 36530974, 2022). "In summary, our first pan-cancer analysis of MFAP2 suggested that MFAP2 could affect clinical prognosis in various cancers and immune cell infiltration, which deepened the understanding of the MFAP2 role in tumorigenesis." (PMID 35211173, 2022). "Therefore, we analyzed the interaction of MFAP2 with various immune cell infiltration in multiple TCGA cancers by searching TIMER and TISIDB databases or by MCP and XCELL algorithms." (PMID 35211173, 2022). "Growing evidence suggests that MFAP2 plays a crucial role in the development of malignant tumors." (PMID 36204318, 2022). "We found that more than a few cancers once had MFAP2 elevated." (PMID 35356627, 2022).
cancer (continued). "The correlation between MFAP2 and gene mutations further suggested its importance in tumorigenesis, although such mutations did not produce tumor neoantigens in most cancers." (PMID 35211173, 2022). "Recently, MFAP2's role in carcinoma has attracted much attention." (PMID 34868341, 2021). "We then explored whether the promoter region of MFAP2 was methylated low in human cancers using TCGA data available on MethHC." (PMID 32054827, 2020). "Most of them participate in matrix remodeling during cancer progression, including MFAP2." (PMID 32054827, 2020). "Subsequent experiments indicated that silencing and exogenous MFAP2 could affect motility of cancer cells." (PMID 32054827, 2020). "The mechanism of how MFAP2 exhibits functions in cancers remains to be studied in detail." (PMID 32054827, 2020). "We first investigated whether MFAP2 locus is amplified in human cancers using TCGA data on cBioPortal." (PMID 32054827, 2020). "The results of the studies suggest that MFAP2 may promote the development of various cancers." (PMID 38822944, 2024). "However, the expression profile of MFAP2 in various cancers and its impact on prognosis and immune infiltration remain unclear." (PMID 35211173, 2022). "Data from the Cancer Cell Line Encyclopedia (CCLE, Xena database) revealed MFAP2 expression was relatively low in the EAC cell line OE19 and some ESCC lines, including KYSE-30, KYSE-70, KYSE-150, and KYSE-450, but high in other ESCC lines." (PMID 40657371, 2025). "Further validation in four independent cohorts showed that KEAP1, SRI, MFAP1, MFAP2, INCENP, and KIF21B were consistently upregulated in cancer tissues, while MYOZ3, DST, and TIAM1 were consistently downregulated." (PMID 40228435, 2025). "Heatmap results showed that NRP1, MFAP2, KLC1, DST, and MYOZ3 were generally downregulated in cancer cell lines, while KIF21B, SRI, INCENP, and KEAP1 were also downregulated." (PMID 40228435, 2025). "Research has found that MFAP2 facilitates FOXM1 expression and regulates glycolysis in oriental cancers through the FOXM1/β-catenin signaling pathway." (PMID 38822944, 2024). "MFAP2 dysregulation greatly changes the ECM status in the cancer microenvironment, modulating the cancer cell phenotypes." (PMID 36530974, 2022). "We have studied MFAP2 expression in belly adenocarcinoma (STAD) and many different types of cancer in humans in the present work." (PMID 35356627, 2022). "To investigate the relationship between MFAP2 expression levels and prognosis in terms of DFI, DSS, OS, and PFI, we depicted forest plots for each cancer." (PMID 35211173, 2022). "To gain insight into the molecular mechanisms behind the adipocyte-cancer cell crosstalk, we evaluated the effect of ACM on the mRNA levels of MFAP2 in HT-29 cells." (PMID 34445187, 2021). "Protein carriers between cancer cells and ECM such as exosome were potential mediators to transport MFAP2 to cancer microenvironment, and this need to be further explored and validated." (PMID 32054827, 2020). "Among them, those highly correlated with different pathological stages are LANCL3, MFAP2 and PPA1, showing consistent up- and down-regulation, respectively, along with cancer progression." (PMID 21445269, 2011). "In vivo xenograft assays showed that MFAP2 enhanced the growth of the KYSE-450 cancer cell line, though no statistical difference was observed in KYSE-140." (PMID 40657371, 2025). "In contrast to MFAP2, the expression of MFAP4 and MFAP5 was downregulated in cancer tissues." (PMID 40657371, 2025). "As shown, the methylation level of MFAP2 promoter was also not significantly decreased in cancer tissue." (PMID 32054827, 2020). "However, there are no pan-cancer studies on the relationship between MFAP2 and various cancers." (PMID 35211173, 2022).
tumor (27 papers, 2008 to 2026). "In general, MFAP2 showed distinct expression in most tumor and normal tissues, closely associated with higher tumor grade, higher tumor stage, and poor survival in multiple cancers." (PMID 35211173, 2022). "Notably, among the genes, MFAP2, encoding the Microfibril Associated Protein 2, was reported to be involved in tumor cell invasion and metastasis." (PMID 40552117, 2025). "In addition, we explored the relationship between MFAP2 expression and gene mutations, promoter methylation, tumor neoantigens, tumor mutation burden (TMB), microsatellite instability (MSI), mismatch repair (MMR) genes, and immune infiltration." (PMID 35211173, 2022). "Notable, three compounds were discovered that effectively bind and down-regulate MFAP2, which significantly impairs tumor cells migration." (PMID 41716634, 2025). "Considering our previous clinical data showed that MFAP2 expression was related to tumor stage, we performed nude mice xenograft assays to better evaluate its role in ESCC." (PMID 40657371, 2025). "Bioinformatics analysis revealed a positive correlation between MFAP2 expression and anti-tumor (M1 type) macrophages in EAC tissues, whereas in ESCC tissues, MFAP2 correlated positively with non-activated (M0 type) macrophages." (PMID 40657371, 2025). "We discovered a weakly significant connection between MFAP2 expression and tumor purity (r = 0.075, P < 0.05)." (PMID 38822944, 2024). "The expression of MFAP2 in tumor tissues was measured by immunohistochemistry and then correlated with the clinical characteristics and prognosis of CRC patients." (PMID 36583532, 2023). "As a result, 171 paired samples were recruited to compare the expression of MFAP2 between tumor and tumor‐free tissues, while 174 CRC samples were used to correlate the expression of MFAP2 with clinical characteristics." (PMID 36583532, 2023). "In order to recognize the involvement of m1A+MFAP2 in the clinical stages of CRC, the m1A methylation of MFAP2 mRNA in tumor tissues from 27 CRC patients was measured." (PMID 36583532, 2023). "Statistical analysis showed that the expression of MFAP2 in CRC tissues was significantly higher than that in tumor‐free tissues." (PMID 36583532, 2023). "The Kaplan–Meier analysis showed that CRC patients with high MFAP2 expression in tumor tissues had a lower overall survival rate than those with low MFAP2 expression (p = 0.020)." (PMID 36583532, 2023). "Here we counted the number of neoantigens for each tumor sample separately and analyzed the relationship between MFAP2 expression and antigens number." (PMID 35211173, 2022). "Recently, it was found that MFAP2 affects different tissue tropisms, playing an important role in regulating steady tissue state, cell survival, and tumor progression." (PMID 36530974, 2022). "These outcomes correspond with a former report that MFAP2 promotes epithelial-mesenchymal transformation, proliferation, and migration in tumor cells." (PMID 36204318, 2022). "Targeting MFAP2 is important in inhibiting tumor cell proliferation, migration, invasion, angiogenesis, and promoting tumor cell apoptosis." (PMID 36530974, 2022). "We analyzed the immune and stromal scores of each tumor sample using the R package ESTIMATE to observe the relationship between MFAP2 expression in 33 tumors and the StromalScore, ImmuneScore, and ESTIMATEScore." (PMID 35211173, 2022). "Despite unclear underlying mechanisms, the correlation between MFAP2 and CD276 in a variety of tumors suggests that MFAP2 is a promising target for tumor immunotherapy." (PMID 35211173, 2022). "Of the overlapping set of proteins, the levels of WFDC2, S100P, CD55, MDK, THBS2, and MFAP2 were more than 2-fold higher in PDAC compared with tumor-adjacent tissue in our data." (PMID 36923555, 2022).